FOXP3 (forkhead box P3)
Diseases named in the same sentence as FOXP3 in open-access papers (continued):
Sharing a sentence is not in itself a finding about the gene and the disease.
breast carcinoma (continued). "It was identified as an abundant protein in breast tumors and correlates with aggressiveness and metastasis of breast cancer because it enhances the pro-tumor Th2 response and triggers the expansion of CD4+ CD25+ Foxp3+ Tregs cells." (PMID 35335881, 2022). "An increased CD8/FOXP3+ TIL ratio in pretreatment biopsies significantly correlated with pCR in TNBC and HER2-positive breast cancer, following FEC100 and paclitaxel + trastuzumab respectively." (PMID 35163586, 2022). "In a breast cancer drug test, tremelimumab significantly increased the ratio of ICOS+/FoxP3+ CD4+ T cells in most patients and stablized the disease for more than 12 weeks in 42% of patients." (PMID 35799609, 2022). "In breast cancer patients, a high amount of TGFβ released by tumor cells, combined with sustained TCR-stimulation, increases the acquired expression of FOXP3 in CD4+CD25- T cells, allowing them to develop into Treg cells." (PMID 35222362, 2022). "Overexpression of the FOXP3 protein not only lessened the proliferative effects of EZH2, but also enhanced degradation of the EZH2 protein in breast cancer models." (PMID 33800594, 2021). "Calycosin in a higher dose significantly reduced the expression levels of the forkhead box P3 (Foxp3), followed by downregulation of VEGF and MMP-9 in MCF-7 and T47D breast cancer cells." (PMID 34462889, 2021). "To explore the clinical significance of FOXP3 and MTA1 expression in the development of breast cancer, we evaluated FOXP3 and MTA1 expression in 92 breast cancer tissues." (PMID 34307133, 2021). "However, recent work including all subtypes of breast carcinomas concluded that CD3+, CD8+ and FOXP3+ lymphocyte densities did not add prognostic information over stromal TILs assessed on H&E in early intermediate/high-risk breast cancer treated with adjuvant chemotherapy." (PMID 34135901, 2021). "On this premise, we verified that FOXP3 expression and MTA1 expression were negatively correlated in breast cancer tissues." (PMID 34307133, 2021). "We transfected Si-FOXP3 and Si-MTA1 into MCF-7 breast cancer cells and determined the mRNA expression levels of the selected potential downstream molecules of MTA1 through real-time PCR." (PMID 34307133, 2021). "Moreover, miR-155, induced by FOXP3 through transcriptional repression of BRCA1, is associated with tumor initiation in human breast cancer, suggesting that plasma miR-155 may serve as a non-invasive biomarker for detection of early-stage breast cancer." (PMID 34768829, 2021). "Then, we confirmed that FOXP3 can inhibit the expression of MTA1 by binding to the promoter of MTA1 and thus reduce the ability of breast cancer cells to metastasize." (PMID 34307133, 2021). "To further verify the correlation between FOXP3 and MTA1 expression in breast cancer, we downloaded and analysed breast cancer case data from public databases." (PMID 34307133, 2021). "Immunohistochemistry was adopted to explore the correlation between the expression levels of FOXP3 and MTA1 in breast cancer samples." (PMID 34307133, 2021). "We initially focused on transcription factors with reported links to breast cancer, and found that 16 transcription factors including HIF-1α, MYC, FOXP3, and E2F1 were predicted to target the JFK locus." (PMID 34336836, 2021). "They found that TNBC patients with a high CD8+ TILs level or high CD8/Foxp3 ratio in residual tumors exhibit significantly favorable recurrence-free survival (RFS) and breast cancer-specific survival (BCSS)." (PMID 34283088, 2021). "To this end, we obtained FFPE tumor tissue from the same breast cancer patients assessed before for TCR clonality in PB and performed Immunofluorescence analysis on serial tissue sections against CD4, FOXP3, and CD127." (PMID 33602930, 2021). "In summary, through in vitro cell assays, in vivo animal experiments, and analysis of clinical breast cancer samples, we systematically confirmed the regulation of MTA1 expression by FOXP3 and clarified its mechanism." (PMID 34307133, 2021).
breast carcinoma (continued). "Later their group found that tumor-infiltrating CD4+CD25+FOXP3+ T cells were a major source of RANKL production in breast cancer and stimulated breast cancer metastasis through RANKL–RANK signaling." (PMID 33795653, 2021). "Forkhead box protein P3 (FOXP3) is involved in regulatory T (Treg) cell development and inhibits tumorigenicity by downregulating oncogenes such as HER2/ErbB2 in breast cancer." (PMID 33968766, 2021). "IFNγ and FOXP3 expressions were detected in cells cocultured with CD4 T cells and breast cancer cells." (PMID 34659411, 2021). "Here, we performed an exploratory analysis to examine the prognostic impact of CSF-1R+ carcinoma cells in the context of iTIL subsets expressing CD8 or FOXP3 in ER-positive breast cancers in the combined cohort of the BC Cancer series with complete 20-year follow-up information (n = 1666)." (PMID 34830923, 2021). "The serum CTLA-4, TNF-α and IL-6 levels of 57 female cats with mammary carcinoma were determined by ELISA, and immunohistochemistry was performed to evaluate CTLA-4 and FoxP3 expression in tumor cells and interstitial lymphocytes." (PMID 32123292, 2020). "Taken together, our results successfully demonstrated that the expression of the immune cell subtype-related proteins STAT6, FOXP3, CD8, CD68, and CD163 was different according to the molecular subtype of breast cancer." (PMID 32580398, 2020). "Yet, in the case of FOXP3, when the results were analyzed by classification into low and high groups, high FOXP3 expression was reported in 70% of TNBC and 67% of HER-2-positive breast cancer, which is similar to our study." (PMID 32580398, 2020). "FoxP3+ Treg cells express receptor activator of nuclear factor-κB (RANK) ligand (RANKL), which stimulates the pulmonary metastasis of RANK+ breast cancer cells." (PMID 33234169, 2020). "Univariate analysis of pathological features, CCL20 expression, and FOXP3+ TILs infiltration with OS and DFS in breast cancer patients (n = 156)." (PMID 31852159, 2019). "Multivariate Cox regression analysis indicated that both FOXP3 and CCL20 are independent prognostic factors for OS of breast cancer patients." (PMID 31852159, 2019). "We investigated the effect of anti-PD-1, anti-PD-L1 or both mAbs on the expression of ICs, FoxP3 and Helios in CD4+CD25− T cells in the presence of breast cancer cells." (PMID 31614877, 2019). "We further evaluated the effects of FOXP3 and CCL20 expression on survival outcomes in breast cancer patients under different lymph node metastasis status." (PMID 31852159, 2019). "We determined the kinetics and level of expression of key inhibitory ICs (PD-1, CTLA-4, TIM-3 and LAG-3) and Treg-related markers (FoxP3 and Helios) in CD4+ T cells in the absence or presence of breast cancer cells." (PMID 31614877, 2019). "Next, we examined the effect of anti-PD-1, anti-PD-L1 or both mAbs on the expression of ICs, FoxP3 and Helios in CD4+CD25+ T cells in the presence of breast cancer cells." (PMID 31614877, 2019). "We evaluated the prognostic significance of FOXP3+ TILs and CCL20 expression in breast cancer and conducted clinical follow-ups." (PMID 31852159, 2019). "In order to determine the role of CCL1 and CCL22 on Treg attraction to breast cancer, we analyzed 199 breast cancer tissue samples that were previously stained for expression of CCL1, CCL22 and FoxP3." (PMID 30572845, 2018). "In breast cancer, the frequency of CD4+CD25+FoxP3+ regulatory T cells was inversely correlated with clinical outcomes." (PMID 28669079, 2018). "The present study investigated the clinical significance and value of changes in the levels of CD8+ TILs and FOXP3+ TILs and the CFR before and after NAC in all breast cancer subtypes." (PMID 30233820, 2018). "Collectively, these analyses partially suggest that simultaneous FOXP3 downregulation and VEGF upregulation is correlated with reduced breast cancer survival." (PMID 29970908, 2018).
breast carcinoma (continued). "We investigated the clinical significance of CD4, forkhead box P3 (FOXP3), and B cell attracting chemokine leukocyte chemoattractant-ligand (C-X-C motif) 13 (CXCL13) in early breast cancer." (PMID 29482642, 2018). "In summary, this investigation has demonstrated that FOXP3, one of the FOX protein family members, is a novel activator of the human UBC9 promoter in MCF7 breast cancer cells." (PMID 30011797, 2018). "Expression of ZEB2 was significantly reduced (mRNA by 41.5% and protein by 48.0%) in FOXP3 + BT549 cells, compared with GFP + BT549 cells, indicating that the endogenous ZEB2 gene is regulated by FOXP3 in breast cancer cells." (PMID 29963231, 2018). "However, it is unclear whether FOXP3 is involved in the regulation of breast cancer angiogenesis." (PMID 29970908, 2018). "Thus, our data suggest that FOXP3 might be an angiogenic suppressor in breast cancer." (PMID 29970908, 2018). "The treatment response after NAC tended to improve in breast cancer patients with high FOXP3+ TILs, low NLR (neutrophil count/ALC) (FOXP3 p for trend = 0.006, NLR p for trend = 0.063)." (PMID 30285668, 2018). "Similar results were observed using a second highly invasive breast cancer cell line MDA-MB-231; cells transfected with miR-155 relative to miR-control transfected cells (40%, 24%, 14% increased migration in WT, GFP and FOXP3 cells respectively)." (PMID 29963231, 2018). "FOXP3 also acts through vascular endothelial growth factor (VEGF) to inhibit angiogenesis, as observed in breast cancer." (PMID 30360388, 2018). "In breast cancer, both CD8+ and Foxp3+ TILs increased after NAC, but CD8+ lymphocytes increased more dramatically resulting an elevated CD8+/FOXP3+ ratio." (PMID 30474571, 2018). "In order to investigate the role of CCL1 and CCL22 on Treg infiltration and overall survival in breast cancer patients, we stained tissue microarrays of 199 breast cancer patients for the CCL1, CCL22 and FoxP3." (PMID 30572845, 2018). "However, the biological functions of FOXP3 in breast cancer angiogenesis remain unclear." (PMID 29970908, 2018). "We stained tissue microarrays (TMA) of 199 breast cancer patients for expression of CCL1, CCL22 and FoxP3." (PMID 30572845, 2018). "Therefore, we evaluated whether FOXP3 can regulate VEGF expression in breast cancer." (PMID 29970908, 2018). "There were, however, significantly higher levels of tumour-infiltrating FOXP3+ and CTLA-4+ T cells in ALN metastases compared with the levels in the corresponding primary breast cancers (p = 0.026, p = 0.036, respectively)." (PMID 29390966, 2018). "Vimentin staining and also filamentous actin (F-Actin) staining were much more intense and widespread in the FOXP3 knockdown cells, with the Vimentin staining in these cells resembling that of highly invasive BT549 breast cancer cells." (PMID 29963231, 2018). "FOXP3 targets and transcriptionally inhibits the breast cancer suppressor gene, BRCA1, which reduces the radioresistance of breast cancer cells." (PMID 28562349, 2017). "We first compared Treg frequencies by flow cytometry in PB and BM of healthy individuals (PB n = 7 and BM n = 8) and 50 breast cancer patients using CD25, FoxP3, and CD4 as Treg markers." (PMID 28224210, 2017). "In the breast cancer tissue sections studied, there was in situ expression of IL-10 and TGF-β and therefore the likely presence of induced FOXP3+ Tregs." (PMID 27777963, 2016). "Several T-cell phenotypes and functional markers have been investigated as potential prognostic and predictive factors in breast cancer, such as CD8+ T-cells, FoxP3 and the ζ-chain of the T-cell receptor." (PMID 27473163, 2016). "Both Foxp3+ TILs and CD8+ TILs also had some relationships with breast cancer clinicopathological parameters." (PMID 26459255, 2016). "It is already known that TILs in breast cancer have several subtypes, such as CD8+ T cell, PD-1+ T cell and Foxp3+ T cell." (PMID 26459255, 2016).
breast carcinoma (continued). "Two brain metastases cohorts, a mixed entity cohort (n = 252) and a breast carcinoma validation cohort (n = 96) were analyzed for CD3+, CD8+, FOXP3+, PD-1+ lymphocytes and PD-L1+ tumor cells by immunohistochemistry." (PMID 26517811, 2015). "To further confirm the role of CD4+ and CD8+ T cells in human breast cancer development and progression, we assessed CD4+ and CD8+ T cells, as well as IL-17+ and Foxp3+ cells in breast tumor tissues from cancer patients using the immunohistochemical staining." (PMID 25968569, 2015). "TNBC patients with high CD8+ TIL levels or a high CD8/FOXP3 ratio in residual tumors had significantly better recurrence-free survival (RFS) and breast cancer-specific survival (BCSS) than patients with low values of these parameters." (PMID 26341640, 2015). "Studies from the retrospectively analyzed clinical tumor tissues of breast cancer patients further demonstrated that tumor-infiltrating CD8+ T cells and FoxP3+ T cells are important components for assessing disease prognosis and clinical progression." (PMID 25968569, 2015). "The most commonly tested markers for TILs subset tested in breast cancer are CD3+, CD4+, CD8+ and FOXP3+." (PMID 25501357, 2014). "TILs subset in breast cancer, primarily CD3+, CD4+, CD8 and (regulatory T-lymphocytes expressing forkhead box P 3 protein) FOXP3+ lymphocytes, have also been studied in the relationship of the pCR rate." (PMID 25501357, 2014). "The results from our study suggest that both FOXP3+ and CD8+ T-cell infiltration have distinctive prognostic implications in different molecular subtypes of breast cancer." (PMID 25193543, 2014). "In the setting of NCT for breast cancer, mixed results for the diverse TIL subpopulations, such as CD8 or Foxp3, have been found in different studies." (PMID 25432519, 2014). "This study only assessed the interaction between FOXP3+ and CD8+ T-cell infiltration in breast cancer; further studies need to be done to differentiate other types of chronic inflammatory infiltration." (PMID 25193543, 2014). "FOXP3+ regulatory TILs were a favorable prognostic factor in the HER2+/ER− breast cancers, but an adverse prognostic indicator in ER+ breast cancer." (PMID 25540645, 2014). "There was a significant correlation (Spearman’s Rho p = 0.04, 2-tailed) between the % of FOXP3+ Tregs (prior to NAC) and the subsequent pathological grade of response in the breast cancer following 8 cycles of NAC." (PMID 23320561, 2013). "FOXP3 was shown to be involved in the induction of several tumor suppressors, including p21, p18, LAT2, and ARHGAPS in breast cancer." (PMID 23888189, 2012). "A tissue microarray (TMA) including 894 ductal and 164 lobular breast cancers was stained with antibodies recognizing CD4, FOXP3, and IL-17 by standard immunohistochemical techniques." (PMID 22471961, 2012). "In this study, the expression of IDO in primary breast cancer was examined and the correlation between the expression levels of IDO and the densities of Foxp3+ Tregs in situ was studied." (PMID 22110525, 2011). "Immunoperoxidase staining for FOXP3 and CXCL12 was performed on tissue microarrays from 491 breast cancers." (PMID 21521526, 2011). "In this study, we investigated FOXP3+ Tregs and TIL-expressing B7-H1 and its ligand PD-1 in breast cancer patients." (PMID 18294387, 2008). "This is the first study to investigate the correlation between FOXP3+ Tregs and TIL-expressing B7-H1 and PD-1 in breast cancer patients." (PMID 18294387, 2008). "For luminal breast cancers, we found that high WWOX/HIF1A ratios demonstrate a more robust anti-tumour immune response, as evidenced by increased expression of CD8A and FOXP3, which are instrumental in recruiting cytotoxic T-cells and suppressing pro-tumourigenic inflammation." (PMID 41007296, 2025).
breast carcinoma (continued). "Interestingly, since the expression of CCR4 is higher in Tregs than other CD4+ T cells, probably because of a FOXP3 responsive element on the CCR4 promoter, Tregs infiltration is favored in some tumors, e.g., in breast cancer." (PMID 39596815, 2024). "Researchers showed that UBC9 was upregulated through Forkhead Box Protein P3 (FOXP3), a tumor-suppressing TF, which could act as a novel activator of SUMOylation in Breast Cancer (BRCA)." (PMID 37415251, 2023). "Previous study demonstrated that Tregs Foxp3 expression level was directly connected to the level of STAT3 in skeletal immune system and breast cancer, and STAT3 activity is also correlated with poor prognosis in EC patients who had undergone surgical resection or chemoradiotherapy." (PMID 36226375, 2023). "Considering that we and others had previously shown that human and murine breast cancer (BRCA) cells express Foxp3, we hypothesized that the mechanism involved in the regulation of Foxp3 expression in Tregs was similar in BRCA cells." (PMID 37766222, 2023). "In this study, we focused on the immunological functional heterogeneity of FOXP3 + TILs and evaluated the balance of eTreg and CD8 TILs as representative of the immunoprogressive and immunosuppressive power of TILs in patients with breast cancer." (PMID 35438346, 2022). "And in breast cancer cell lines, lncRNA DRAIC was up-regulated by FOXP3 and promoted cell migration and invasion via the miR-432-5p/SLBP axis.Moreover, lncRNA DRAIC improved esophageal cancer Eca-109 and EC9706 cell invasion through binding to miR-149-5p, which regulated NFIB levels." (PMID 35992823, 2022). "Simultaneously, the negative prognostic significance of FoxP3+ TIL densities in ER+ breast cancer depended on the absence of CD8+ T cells." (PMID 35140715, 2022). "Furthermore, tumor-infiltrating immune cells (such as CD4+, CD8+, CD56+, and Foxp3+ cells) in E0771 and 4T1 breast cancers treated with SI-2 and in SRC-3 KD E0771 and 4T1 breast cancers were determined by immunohistochemistry." (PMID 36316775, 2022). "IGF1R signaling negatively impacts immune surveillance in breast cancer patients, as evidenced by IGF1R phosphorylation resulting in slight CD8+ CTL infiltration, significant infiltration of FOXP3+ regulatory T cells, immunosuppressive CD163+ macrophages, and poor prognosis." (PMID 35463082, 2022). "For example, FOXP3 downregulates VEGF, leading to inhibition of angiogenesis in breast cancer." (PMID 36077026, 2022). "Moreover, the PPI network uncovered the crucial roles of numerous proteins (e.g., FOXP3, STAT1, STAT4, FOXP3, JUN, and CD3D) in breast cancer." (PMID 36704358, 2022). "Additionally, we found that FOXP3 had a significant positive correlation with PDCD1, CD274, CTLA4 and TMB in breast cancer." (PMID 35614183, 2022). "A study on plasmacytoid dendritic cells (pDCs) from breast cancer patients showed that excessive accumulation of lactate in the TME enhances tryptophan metabolism and kynurenine secretion by pDCs, leading to the induction of FoxP3+ Tregs." (PMID 33532902, 2021). "FOXP3 may behave as a transcriptional repressor of SKP2 and HER2, acting as a potential tumor-suppressor gene in breast cancer, prostate, gastric cancer, or hepatocellular carcinoma." (PMID 33671179, 2021). "Furthermore, we analysed the correlation between FOXP3 and MTA1 expression in 92 breast cancer tissues." (PMID 34307133, 2021). "Naringenin could block the secretion of TGF-β1 from breast cancer cells, reducing the percentage of CD4+ CD25+ Foxp3 + T cells and suppressing tumor cell migration as well as lung metastasis." (PMID 33572626, 2021). "In addition, the distribution of circulating CD4 + CD25 + FOXP3+ Treg lymphocytes and CD19 + CD24 + CD38 + B lymphocytes significantly increased in breast cancer patients compared with healthy controls using blood samples." (PMID 33726701, 2021).